SNORD1C (small nucleolar RNA, C/D box 1C)
Synonyms: R38C; snR38C
Gene: Small nucleolar RNA gene on chromosome 17 (76,558,791 to 76,558,868, forward strand). Ensembl gene ENSG00000274091.
Gene Ontology:
Biological process: RNA processing
Cellular component: nucleolus
Homologues: Orthologues: chimpanzee SNORD1C (100% identical), macaque SNORD1C (97% identical), pig SNORD1C (86% identical), mouse Snord1c (78% identical), mouse Gm24253 (76% identical), mouse Snord1b (74% identical), rat Snord1b (73% identical), guinea pig SNORD1C (72% identical). Paralogues in human: SNORD1B (71% identical), SNORD1A (58% identical).
Diseases named in the same sentence as SNORD1C in open-access papers:
SNORD1C is named in the same sentence as 2 diseases in open-access papers, as found by Europe PMC text mining. Sharing a sentence is not in itself a finding about the gene and the disease. The quoted sentences say what the papers report.
tumor (1 paper, 2023). "For example, SNORA21, SNORA24, and SNORA42 are upregulated in CRC and promote tumor growth both in vivo and in vitro; SNORD1C maintains the stemness of CRC cells and resistance to the chemotherapeutic drug 5-FU by activating the Wnt pathway." (PMID 37907779, 2023).
SNORD1C also shares sentences with these, for which no sentence is quoted: lung disease (1 paper).